PTBP1 (polypyrimidine tract binding protein 1)
Diseases named in the same sentence as PTBP1 in open-access papers (continued):
Sharing a sentence is not in itself a finding about the gene and the disease.
tumor (continued). "From immunostaining of the tumor areas in the brain sections, we found that both SON expression and PTBP1 expression levels are significantly downregulated in tumors formed by SON shRNA-expressing GSCs, consistent with our in vitro data." (PMID 34548489, 2021). "It has been known that PTBP1 induces skipping of RTN4 exon 3, generating the transcript (RTN4-B) for the Nogo-B protein which promotes tumor angiogenesis, epithelial-mesenchymal transition, cell migration, and proliferation." (PMID 34548489, 2021). "Regarding the other RNAs analysed, they revealed to be upregulated in most of the tumours, namely CCND1 (52%), PKM2 (67%) and PTBP1 (46%)." (PMID 31461477, 2019). "By fusing a gasdermin D mutant to a mitochondrial-targeting peptide, they harnessed mitochondrial inner membrane cardiolipin toxicity to trigger mitophagy-mediated tumor cell death, which markedly suppressed tumor growth in xenograft models of EIF4G2+/PTBP1+ adenocarcinomas." (PMID 41226581, 2025). "Immunohistochemical analysis revealed that EP300-AS1 knockdown increased PRMT5 and Ki67-positive cell number without affecting PTBP1 levels, supporting the tumor-suppressive role of EP300-AS1." (PMID 40790019, 2025). "Western blot analysis of tumor tissues showed no significant changes in c-MYC protein levels but revealed reduced PTBP1 protein and c-MYC S62 phosphorylation levels, along with increased levels of Atg10, Beclin-1, P62, and LC3B." (PMID 40469179, 2025). "In addition, PTBP1 can also boost the expressions of cell-cycle-related proteins such as cyclin A, cyclin B, cyclin D, cyclin E, and CDC2, to promote tumor cell proliferation." (PMID 38785973, 2024). "The results showed that the level of PTBP1 was significantly increased in distinct tumors including LUAD, suggesting that PTBP1 may play an oncogenic role in tumor development." (PMID 39057099, 2024). "First and foremost, to elucidate the effect of PTBP1 on the proliferation of xenograft tumours in vivo, we conducted xenograft where 2 × 106 HGC-27 cells with PTBP1 knockdown or overexpression or respective control were subcutaneously inoculated into the BALB/c nude mice." (PMID 36635500, 2023). "The results showed that ASEs up-regulated in BLCA with high-level neoplasm grade were enriched to several RBPs’ motifs, including “poly-T” motifs and polypyrimidine tract (Py-tract) sequence of HuR, CPEB4, TIA1, HNRNPC, PTBP1, RALY and ZC3H14, and motifs of PCBP2 and SNRNP70." (PMID 37810965, 2023). "Consistently, ITSN1-L knockdown on top of PTBP1 silencing manifested no significant impact on tumor growth and final tumor volume compared with the control group." (PMID 36171198, 2022). "Meanwhile, the mRNA expression of PTBP1 and SLC39A1 was significantly negative related to tumor purity (PTBP1, r = − 0.15; SLC39A1: r = − 0.61; P < 0.05)." (PMID 36307882, 2022). "And the mRNA expression of MMP9 and SLC16A3 was significantly negative related to tumor purity (PTBP1, r = − 0.53; SLC39A1: r = − 0.58; P < 0.05)." (PMID 36307882, 2022). "We still cannot exclude the possibility that high PTBP1 phosphorylation of S459 is a byproduct of dysregulated signaling with no functional significance in tumor cells." (PMID 36595978, 2022). "Moreover, despite the fact that MALAT1 is considered as a broad-spectrum tumor-promoting transcript, the functional module consisting of MALAT1, PTBP1, and PSF appears to have greater clinical value in HCC." (PMID 36563164, 2022). "Additionally, circFOXP1 regulates the Warburg effect by interacting with PTBP1 to up-regulate the expression of PKR and exert its pro-tumor effect, eventually protecting PKLR from mRNA degradation." (PMID 34445958, 2021). "Our GBM orthotopic xenografts also confirmed that SON reduction in GSCs leads to depletion of PTBP1 as well as the well-known GBM stemness marker SOX2, suggesting targeting SON efficiently suppresses the tumorigenic ability of GSCs and inhibits tumor cells’ stemness in vivo." (PMID 34548489, 2021).
tumor (continued). "RT-qPCR results further revealed that PTBP1 expression was higher in tumor tissues derived from non-responders to doxorubicin (DXR) than that in tumor tissues derived from responders (p < 0.05)." (PMID 33621196, 2021). "For example, PTBP1 enhances the PKM2 isoform and reduces the PKM1 isoform by controlling PKM alternative splicing, which promotes aerobic glycolysis and provides a selective advantage for tumor formation." (PMID 34706749, 2021). "PTBP1 was upregulated in tumor tissues derived from non-responders to DXR treatment and correlated with patient poor survival." (PMID 33621196, 2021). "Likewise, circMYBL2 promotes FLT3 kinase translation by strengthening the binding of PTBP1 to FLT3 mRNA, which regulates FLT3 kinase level and activation of FLT3-ITD-dependent tumor signaling pathways." (PMID 34445958, 2021). "The results showed that the expression of PTBP1 was not correlated with age, gender, location of tumorigenesis, pathological classification and pathological grading of tumours." (PMID 32207235, 2020). "PTBP1 promotes the skipping of exon 6 in ANXA7 and expression of this isoform diminishes the endosomal internalization of EGFR, thus enhancing signaling during tumor progression." (PMID 31861467, 2019). "Similarly, the high expression of PTBP1 (also known as hnRNPI) and/or its amplification in GBM maintain progenitor-specific splicing patterns that counteract tumor suppressor functions and favor tumor progression." (PMID 31861467, 2019). "Notably, the up-regulation of PTBP1 in GBM alters the splicing of Annexin A7 (ANXA7), a membrane-bound tumor suppressor protein involved in endosomal organization and function." (PMID 31861467, 2019). "Taken together, above results suggest that the role of PTBP1 in tumorigenesis may be partly mediated by its regulation of CDC42 alternative splicing and CDC42-v2 might function as a tumor suppressor." (PMID 26336992, 2015). "In addition, PTBP1 modulates the stability of the myeloid cell leukemia 1 (MCL1) transcript and promotes the accumulation of MCL1 in the cytoplasm, which inhibits the apoptosis of tumor cells." (PMID 39366930, 2024). "Moreover, PTBP2, rather PTBP1, in mediastinal NB with a favorable outcome was also found to be abundantly expressed on the basis of sequence data, hinting that PTBP2-mediated alternative splicing exerted a tumor-inhibiting effect in NB." (PMID 37040518, 2023). "We finally identified PTBP1 in ACC, KIRP, and LGG; PTBP2 in ACC and KICH; and PTBP3 in ACC, LGG, and PAAD as potential prognostic biomarkers that may be involved in tumor progression in these tumor types." (PMID 36203873, 2022). "A robust correlation between SF3B1 expression and the most critical oncogenic spliceosome components [SRSF3/RBM22/PTPB1/RBM3] was also found in GBM (CGGA- and Rembrandt-datasets), but not in the non-tumor samples (with the exception of PTBP1; Rembrandt-datasets)." (PMID 35086552, 2022). "However, the expression of PTBP1 was not significantly correlated with gender, tumor location, and KPS." (PMID 35299889, 2022). "Furthermore, PTBP1 binds the 5′ UTR internal ribosome entry site in HIF1α mRNA, enhancing HIF1α translation, and accounts for 40–50% of hypoxia-stabilized HIF1α levels, increasing the influence of hypoxia-induced LUCAT1/PTBP1 complexing on tumour suppressor inactivation through alternative splicing." (PMID 32536347, 2020). "The expressions of PPP1R26, PTBP1 and PKM2 were upregulated in 93.8% (15/16), 100% (16/16) and 93.8% (15/16) in human HCC tumor tissues compared with the non-cancerous tissues, respectively." (PMID 35292107, 2022). "The results showed that in most tumor types, the expression levels of PTBP1 and PTBP3 in tumor tissues were significantly higher than that in non-tumor tissues." (PMID 36203873, 2022).
infection (16 papers, 2013 to 2025). The state of being infected such as from the introduction of a foreign agent such as serum, vaccine, antigenic substance or organism. "At a similar time point post-infection, PTBP1 expression was found only mildly reduced by CRISPR/CasRX, and ~ 22% of cells that were infected by the CasRX system were positive for the neuronal nuclear antigen marker (NeuN)." (PMID 39627843, 2024). "Proteins like HuR, the G3BP homologue Rasputin, hnRNP A1, and PTBP1 all have been characterized during infection of mosquito cell culture models." (PMID 36680204, 2023). "Through their recruitment in regulatory complexes during infection with several coronaviruses (CoV), DENV, and Theiler’s murine encephalomyelitis virus (TMEV), PTBP1 depletion has recently been linked to idiopathic Parkinson’s disease (iPD)." (PMID 37446229, 2023). "We detected the cleavage of PTBP1 by 8 hours post-infection, at a time when viral protein production is maximal based on the accumulation of 3CD/3D protein." (PMID 30142213, 2018). "Aside from the strong evidence for SFPQ redistribution during HRV16 infection, SFPQ is also a compelling candidate for involvement in HRV16 replication due to its association with PTBP1 in uninfected cells." (PMID 30142213, 2018). "Notably, this is not the case for all known RNA-binding proteins previously implicated in poliovirus translation; for example, PTBP1 was not enriched on viral polysomes during infection." (PMID 36555135, 2022). "In addition, even though U87 cells have an infection efficiency of more than 97% in vitro, the proliferation rate of uninfected cells in the brain was substantially higher than that of sh-PTBP1 infected cells, resulting in a sharp decline of M-cherry+ U87 cells in vivo to 48.38%." (PMID 35664063, 2022). "An increase in productive infection was detected after knockdown of FLNA, HMGB3, PTBP1, HSP90AA1, and KIF2C (green bars)." (PMID 34194479, 2021). "In direct contrast to PTBP1, the cleaved form of SFPQ was just barely detectable in the cytoplasm at 6 hours post-infection, around the time at which significant levels of viral protein production can be detected." (PMID 30142213, 2018). "Many proteins, including nucleolin, hnRNP A1, PTBP1, La, Sam68, hnRNP K, hnRNP C1/C2, SRSF3, and TDP2, that are relocalized as a result of infection have known functions in the replication cycle of picornaviruses." (PMID 26150805, 2015). "Moreover, the expression of PTBP1 was confirmed in PEDV-infected LLC-porcine kidney 1 (PK1) cells at 20 and 24 h post infection (hpi)." (PMID 37392846, 2023). "Mechanistically, SFPQ appears to exert its pro-viral function subsequent to viral translation, as it does not relocate from the nucleus until around the time PTBP1 is cleaved and viral RNA synthesis has commenced, about 6–8 hours post-infection." (PMID 30142213, 2018). "Indeed, a recent report demonstrated that three HRV serotypes do not induce the cleavage of PCBP2 or PTBP1 during infection of a human lung cell line, suggesting alternative mechanisms must be used under theses experimental conditions." (PMID 26150805, 2015). "However, as with PTBP1 and the EMCV IRES, whether these in vitro systems are representative of the conditions encountered within the cellular milieu during infection, or if other, non-essential, ITAFs enhance viral IRES-driven translation, remains to be elucidated." (PMID 26150805, 2015).
neurodegenerative disease (5 papers, 2022 to 2025). A disorder of the central nervous system characterized by gradual and progressive loss of neural tissue and neurologic function. "Therefore, conversion of glia to neuron using CasRx -mediated knockdown of Ptbp1 shows a potential therapeutic approach for tackling neurodegenerative diseases and brain damage due to neuronal loss." (PMID 35433685, 2022). "Recent studies have shown that downregulation of a single gene, Ptbp1, can lead to the transdifferentiation of astrocytes into neurons, providing new therapeutic options for neurodegenerative diseases." (PMID 40702752, 2025). "Our results and recent findings highlight the potential role of PTBP1 downregulation in neurogenesis and neurodegenerative disease, which necessitates further research." (PMID 41043426, 2025). "This challenge remains, but the fact that Ptbp1 depletion appears to reverse deficits in neurodegenerative disease by turning a specific subpopulation of glial cells into neurons, among other mechanisms, is noteworthy." (PMID 40702752, 2025). "These may provide key insights into the clinical application of PTBP1 downregulation for the treatment of neurodegenerative diseases and clarify the controversies in the literature." (PMID 39627843, 2024).
cardiovascular disease (4 papers, 2020 to 2024). "Concentrations of PFOS and PFOA in infant blood spots were associated with sex-specific changes in DNA methylation at a small number of loci, including the gene PTBP1, related to cardiovascular disease and development." (PMID 36325489, 2022). "Furthermore, we review the current knowledge about the contribution of RBM20 and PTBP1 in heart alternative splicing events, their combinatory role in selecting specific exons and RBM20’s role in cardiovascular diseases." (PMID 32276354, 2020).
cardiac diseases (2 papers, 2020 to 2023). "We also observed that Ptbp1 deficiency affected multiple signaling pathways involved in other cardiac pathological processes, providing insight into PTBP1 and heart diseases." (PMID 37002228, 2023).
movement disorder (1 paper, 2015). Neurological conditions resulting in abnormal voluntary or involuntary movement, which may impact the speed, fluency, quality and ease of movement. "Further, COPZ1, EFTUD2 and PTBP1 mRNAs correlated with clinical features in PD patients including the Hoehn and Yahr scale, Movement Disorder Society revision of Unified Parkinson’s Disease Rating Scale (MDS-UPDRS) and Montreal Cognitive Assessment (MoCA) score." (PMID 26566043, 2015).
neurodevelopmental disorder (1 paper, 2025). A behavioral and cognitive disorder with onset during the developmental period that involves impaired or aberrant development of intellectual, motor, or social functions. "Altered nucleocytoplasmic distribution of the RNA-bining protein PTBP1 results in a syndromic neurodevelopmental disorder associated with skeletal dysplasia." (PMID 40965981, 2025).
PTBP1 also shares sentences with these, for which no sentence is quoted: colitis (4 papers); amyotrophic lateral sclerosis (3); nervous system diseases (3); adenocarcinoma (2); breast tumor (2); cutaneous melanoma (2); diabetic kidney disease (2); fibrosis (2); Multiple Myeloma (2); Parkinson’s (2); rhabdomyosarcoma (2); sarcoma (2); triple-negative breast carcinoma (2); viral infection (2); adrenocortical carcinoma (1); Allergy (1); astrocytic neoplasms (1); benign tumor (1); breast (1); Cerebral ischemia (1); cholangiocarcinoma (1); Cholestatic liver disease (1); colon adenocarcinoma (1); deficient (1); dementia (1); embryonal carcinoma (1); epithelial ovarian tumors (1); esophageal squamous cell carcinoma (1); Ewing sarcoma (1); Familial Platelet Disorder with Associated Myeloid Malignancy (1).
A further 37 diseases each share a sentence with PTBP1 in 1 paper.